TMEM9B (TMEM9 domain family member B)
Description:
Enhances production of pro-inflammatory cytokines induced by TNF, IL1B, and TLR ligands. Has a role in TNF activation of both the NF-kappaB and MAPK pathways.
Synonyms: C11orf15
Tractability: Antibody: UniProt predicts a signal peptide or a membrane-spanning region. PROTAC: ubiquitination databases record sites on it; its protein half-life has been measured.
Gene: Protein-coding gene on chromosome 11 (8,947,202 to 8,965,011, reverse strand). Ensembl gene ENSG00000175348.
Subcellular location: Lysosome membrane; Early endosome membrane
Gene Ontology:
Molecular function: protein binding
Biological process: positive regulation of canonical NF-kappaB signal transduction
Cellular component: early endosome membrane; lysosomal membrane
Genetic constraint (gnomAD): Loss-of-function variants: 7 observed, 18.24 expected, observed/expected ratio (o/e) 0.38, 90% interval 0.22 to 0.72. The upper end of that interval is the gene's LOEUF score, 0.72, which puts it in group 2 of 6, group 1 being the genes least tolerant of losing a copy. Missense variants: 168 observed, 211.41 expected, observed/expected ratio (o/e) 0.79, 90% interval 0.7 to 0.9. Synonymous variants: 97 observed, 83.51 expected, observed/expected ratio (o/e) 1.16, 90% interval 0.99 to 1.38.
Homologues: Orthologues: chimpanzee TMEM9B (100% identical), macaque TMEM9B (99% identical), rabbit TMEM9B (97% identical), mouse Tmem9b (95% identical), rat Tmem9b (94% identical), guinea pig TMEM9B (90% identical), zebrafish tmem9b (75% identical), tropical clawed frog tmem9b (74% identical), dog TMEM9B (73% identical), pig TMEM9B (73% identical), Caenorhabditis elegans R12C12.6 (31% identical), Drosophila melanogaster CG1161 (29% identical). Paralogues in human: TMEM9 (54% identical).
Diseases named in the same sentence as TMEM9B in open-access papers:
TMEM9B is named in the same sentence as 6 diseases in open-access papers, as found by Europe PMC text mining. Sharing a sentence is not in itself a finding about the gene and the disease. The quoted sentences say what the papers report.
Dent disease (1 paper, 2024). Dent disease is a rare genetic renal tubular disease characterized by manifestations of proximal tubule dysfunction. "Moreover, it will be interesting to test whether TMEM9B interacts with the kidney-specific ClC-5 transporter, which is involved in Dent’s disease." (PMID 39202776, 2024).
glaucoma (1 paper, 2024). Increased pressure in the eyeball due to obstruction of the outflow of aqueous humor. "TMEM9B, on the other hand, has not been widely studied in the context of glaucoma, but it is known to be involved in membrane transport processes." (PMID 38287276, 2024). "Some of these autoantibodies react with proteins which have previously been associated with glaucoma, such as LOX and TMEM9B, as well as proteins which have little or no previous association with the disease, such as CDH5 and FUT2." (PMID 38287276, 2024).
osteosarcoma (1 paper, 2022). A usually aggressive malignant bone-forming mesenchymal neoplasm, predominantly affecting adolescents and young adults. "Of the six TMEM genes, the expression of TMEM9B was lower in the high-risk group than in the low-risk group and was positively associated with the overall survival of osteosarcoma patients." (PMID 35991561, 2022). "Moreover, Kaplan–Meier survival analysis revealed that TMEM9B was positively associated with the overall survival of osteosarcoma patients in both TCGA and GSE16091 cohorts." (PMID 35991561, 2022). "Of the six TMEM protein family genes, lower expression of TMEM9B predicted worse overall survival in patients with osteosarcoma." (PMID 35991561, 2022). "Further experiments are needed to explore the effect of TMEM9B knockdown or overexpression on the malignant behaviors of osteosarcoma cells and cell senescence." (PMID 35991561, 2022). "Besides, the effect of knockdown or overexpression of the six TMEM genes, especially TMEM9B, on the malignant behaviors of osteosarcoma cells should be further explored and we will conduct it in the future." (PMID 35991561, 2022). "In conclusion, our TMEM protein family gene-based signature is a novel and clinically useful prognostic biomarker for osteosarcoma patients, and TMEM9B might be a potential therapeutic target in osteosarcoma." (PMID 35991561, 2022). "Besides, we found that the expression of TMEM9B was decreased in osteosarcoma cell lines compared to that in mesenchymal stem cells by analyzing the GSE70414 dataset in the GEO database (data not shown)." (PMID 35991561, 2022). "TMEM9B might be a potential therapeutic target in osteosarcoma." (PMID 35991561, 2022). "Our analyses revealed that TMEM9B might exert a tumor-suppressive role in osteosarcoma." (PMID 35991561, 2022). "Prognosis-related TMEM protein family genes were identified by the univariate Cox regression analysis and were utilized to construct a signature based on six TMEM protein family genes (TMEM120B, TMEM147, TMEM9B, TMEM8A, TMEM59, and TMEM39B) in osteosarcoma." (PMID 35991561, 2022).
cancer (4 papers, 2015 to 2024). A tumor composed of atypical neoplastic, often pleomorphic cells that invade other tissues. "Several papers describe the role of enhanced TMEM9B expression in various types of cancer, possibly via interaction with the vesicular H+-ATPase." (PMID 39202776, 2024). "The physiological role of TMEM9B is unknown, but several papers describe a role of enhanced TMEM9B expression in several types of cancer, possibly via interaction with the vesicular H+-ATPase." (PMID 39202776, 2024). "Several genes (for example, RIPK2, EFNA4 and TMEM9B) showed differential expression in subtypes associated with high proliferation, such as IntClust 5 (predominantly HER2/ERBB2-amplified cancers) and IntClust 10 (predominantly basal expression type cancers)." (PMID 25572802, 2015). "A Tmem9b knockout mouse showed no overt phenotype, but the analysis concentrated on the involvement of the protein in cancer." (PMID 39202776, 2024). "A Tmem9b knockout mouse showed no overt phenotype, but the analysis was focused on the involvement of the protein in cancer." (PMID 39202776, 2024). "Despite these findings, the role of TMEM9B in malignant tumors had not been reported." (PMID 35991561, 2022).
tumor (2 papers, 2011 to 2022).
TMEM9B also shares sentences with these, for which no sentence is quoted: breast carcinoma (2 papers).